RHOA (ras homolog family member A)
Diseases named in the same sentence as RHOA in open-access papers (continued):
Sharing a sentence is not in itself a finding about the gene and the disease.
tumor (continued). "ARHGAP26 (GRAF) belongs to a family of Rho GTPase activating proteins and is a tumor suppressor acting by negatively regulating RhoA, a small GTP-binding protein with a growth-promoting effect in RAS-mediated malignant transformation." (PMID 24886876, 2014). "Consistent with data obtained in tumour cells, Sema4D-induced ErbB-2 phosphorylation and RhoA activation in mouse osteoblasts were sensitive to the inhibition of the IKK-complex." (PMID 25137062, 2014). "RhoB differs from the other GTPases RhoA and RhoC in that it is postulated to be a tumor suppressor because its expression is decreased in a number of tumor cell types." (PMID 25548921, 2014). "Tumor RhoA scores increased with decitabine (P = 0.03), and RFC1 also increased in patients with pre-decitabine scores ≤150 (P = 0.004)." (PMID 24401732, 2014). "In ErbB-2-overexpressing tumour cells, such as BT-474 and MT-2, RhoA activity was strongly reduced by blockade of the IKK-complex or knockdown of Plexin-B1." (PMID 25137062, 2014). "RhoA, a well-known small GTPase, regulates numerous biological behaviors such as F-actin filament formation or rearrangement, which is involved in tumor cell morphology and metastasis." (PMID 25193865, 2014). "Our present results revealed that PIWIL2 induces RhoA expression via regulating c-Myc, modulates F-actin filaments and affects tumor cell invasion and migration." (PMID 25193865, 2014). "It has been reported that RhoA is up-regulated in several types of human cancers, including HCC, and the over-expression of this protein has been positively associated with tumor metastasis and/or poor prognosis." (PMID 24992599, 2014). "Reduced RhoA signaling in combination with active Rac1 is required for stimulation of tumor cell invasion and induction of a spindle shaped cell morphology by Activin B." (PMID 25343250, 2014). "In endothelial cells, activation of Plexin-B1 induces a pro-angiogenic response in a RhoA-dependent manner, which is of particular importance for the neovascularization of tumours." (PMID 25137062, 2014). "In our pilot study, we detected the expression of 4 proteins which were closely related with the invasive potential of tumor cells, including vimentin, RhoA, RhoC and MMP-2." (PMID 24658581, 2014). "The over-activation of RhoA has been found in various tumor cells to regulate tumor cell adhesion, invasion and migration." (PMID 24505392, 2014). "Taken together, these data suggest that CTHRC1 promotes tumor invasion by activating RhoA/ROCK pathway." (PMID 23922981, 2013). "We established previously that RhoA is over-expressed and spontaneously activated in MDA-MB-231, and found that blockage of RhoA expression inhibited cancer cell invasion and tumour growth by more than 80% in a mouse model." (PMID 23388133, 2013). "The inhibition of Rac3 expression in MDA-MB-231 cells blocked the VM; this provides yet another argument for thinking that Rac3 plays a role in tumour aggressiveness, even in cells where the small GTPase RhoA is overexpressed and spontaneously activated." (PMID 23388133, 2013). "Specific GAPs can inhibit the activation of Cdc42, Rac1 and RhoA by increasing intrinsic GTPase activity, leading to suppression of tumor formation." (PMID 23538840, 2013). "As reviewed by Hall, RhoA exerts multiple functions in tumor metastasis by orchestrating the action of multiple downstream effectors and promoting the degradation and reconstruction of the extracellular matrix." (PMID 24351810, 2013). "Rho GTPases such as Rac, Cdc42 and RhoA are signaling proteins that regulate cytoskeleton organization, cell cycle progression, cell survival and migration directly contributing to tumor growth and progression." (PMID 24040362, 2013). "Morellofalvone, a biflavonoid, also inhibited tumor growth and angiogenesis of prostate cancer xenografts in mice by targeting RhoA and Rac1 GTPases." (PMID 22580498, 2012).
tumor (continued). "If this is the case, it would be beneficial to inhibit GEF-H1/RhoA/ROCK/MLC signaling pathway when treated with vincristine to prevent tumor metastasis." (PMID 23057787, 2012). "On the other hand, in some pathological states whereby the type or texture of ECM is altered, such as fibrosis or neoplasia, RhoA activity is correspondingly increased, skewing cell behavior away from differentiation, and towards proliferation and migration." (PMID 21678418, 2012). "Ectopic overexpression of DLC1 in HCC cells expressing oncogenic Ras and containing increased GTP-bound RhoA, abolished the tumor formation." (PMID 22580498, 2012). "HTPB significantly suppresses tumor metastasis partly through inhibition of integrin-β1/FAK/MMP/RhoA/F-actin pathways." (PMID 22279574, 2012). "Mechanistic studies reveal that PRL-3 functions as an initiator of neoplastic angiogenesis by recruiting endothelial cells and stimulates invasion and motility of tumor cells through activating the Rho family of small GTPases such as RhoA and RhoC." (PMID 21589872, 2011). "Immunohistochemical analyses of tumor xenograft sections also revealed the decreased RhoA and RhoC expression in Ad-RhoA-RhoC group." (PMID 20828398, 2010). "After injection intratumorally, the growth speed of tumor xenografts in Ad-RhoA-RhoC group was significantly delayed compared with those in NS and Ad-HK group(P < 0.05)." (PMID 20828398, 2010). "It has also been demonstrated that podoplanin contributes to tumour invasion by binding ERM proteins to activate RhoA resulting in epithelial-mesenchymal transition." (PMID 20196862, 2010). "Cancer cells of tumor tissues in Ad-RhoA-RhoC group demonstrated extensive cell death, whereas in NS group and Ad-HK group resulted in less tumor cell death." (PMID 20828398, 2010). "In normal epithelia, RhoA contributes to the generation of epithelial polarity and junction assembly and function but also affects epithelial disruption during tumor progression." (PMID 20704716, 2010). "The levels of RhoA and RhoC mRNA transcripts and proteins in tumor xenografts were detected by reverse quantitative transcription polymerase chain reaction (QRT-PCR) and immunohistochemical staining respectively." (PMID 20828398, 2010). "In Ad-RhoA-RhoC group, the cancer cells of tumor tissues stained very weakly for RhoA and RhoC, in comparison with NS group and Ad-HK group." (PMID 20828398, 2010). "RhoA participates in oncogenic transformation whereas RhoC promotes tumor metastasis and cell migration." (PMID 19319183, 2009). "The Rho family, a member of the Ras superfamily of low-molecular-weight GTP-binding proteins, contains Rho (e.g., RhoA, B, C), Rac and Cdc42 proteins Previous studies have shown that Rho proteins become deregulated by over expression in tumours." (PMID 19374769, 2009). "The involvement of RhoA in testicular human tumors was demonstrated by increased RhoA mRNA levels in relation to tumour grade." (PMID 18377644, 2008). "The success of C1-N1N2 in discriminating activated Rho in immunofluorescence studies implies that this new tool, in collaboration with currently used RhoA and B antibodies, has the potential to analyze Rho activation in cell function and tumor development." (PMID 18377644, 2008). "These discrepancies possibly reflect different serum treatments of the tumour cells after RhoA activation and point out the peril of an across-the-board inhibition of RhoA as a possible therapy." (PMID 15535843, 2004). "As compared to the normal tissue, about 10–30% of the tumours revealed either enhanced levels of rhoB and rhoC mRNA or even reduced levels of rhoA and rac1 mRNA." (PMID 12237774, 2002). "Ten to twenty per cent of the tumours even showed a >50% reduction in rho mRNA level (i.e. rhoA and rac1)." (PMID 12237774, 2002). "We show that the level of RhoA, RhoB, Rac1 and Cdc42 protein is largely enhanced in all tumour samples analysed (n=15) as compared to normal tissues originating from the same individual." (PMID 12237774, 2002).
tumor (continued). "Furthermore, simvastatin is reported to inhibit tumor growth by repressing the activation of RhoA GTPase and nuclear translocation of YAP1." (PMID 41513610, 2026). "When VEGFA binds to NRP1, it encourages Ras homolog family member A (RhoA) activation, which subsequently contributes to the degradation of cyclin-dependent kinase inhibitor (p27kip1), which in turn encourages the proliferation of tumor cells." (PMID 40277760, 2025). "The incidence of RhoA increased with the advancing tumor stage." (PMID 39887960, 2025). "Matrix stiffness has been documented to regulate the expression of key tumor genes through various signaling pathways, including the integrin β1/Piezo1 activation/Ca2+ influx pathway, RhoA/ROCK pathway, YAP-POSTN-integrin mechanotransduction signaling, and YAP/TEAD4/ACADL axis." (PMID 40867005, 2025). "Consistent with previous studies, TET2 and DNMT3A mutations were observed in non‐tumor cells including myeloid or B‐cells, suggesting early founding mutation in a progenitor cell in a subset of cases, but other mutations like IDH2, RHOA, and CD28 appeared to be tumor‐specific." (PMID 40510016, 2025). "Thus, FPR2 promotes EOC progression by simultaneously enhancing cancer cell mobility through RhoA activation and fostering a pro-tumor immune environment via M2 macrophage polarization." (PMID 40330466, 2025). "Gene set enrichment analysis (GSEA) of our transcriptome sequencing results revealed that the RHOA signalling pathway may contribute to the tumour–suppressive function of GNAQ." (PMID 41362935, 2025). "In addition, we assessed the role of RHOA in tumour growth in vivo by constructing NKTCL xenograft mouse models." (PMID 41362935, 2025). "Notably, targeting lactate production (LDHA inhibitor: sodium oxamate) synergized with RHOA-pathway inhibition (ROCK inhibitor: Y-27632) to suppress tumor progression." (PMID 41291745, 2025). "Chen P believed that miR-130b could regulate RHOA and exhibit tumor suppressor functions in PC by targeting RHOA." (PMID 38607540, 2025). "Functionally, RHOA lactylation promotes tumor cell migration, invasion and metastasis." (PMID 41291745, 2025). "In contrast, inhibition of the RHOA pathway notably promoted tumour growth." (PMID 41362935, 2025). "In other tumor types, MAP4K4 has been implicated in promoting tumor cell invasion and resistance in pancreatic cancer and melanoma through activation of the JNK and RhoA signaling pathways." (PMID 40486910, 2025). "We next evaluated RHOA expression in tumour tissues from 56 NKTCL patients by immunohistochemistry." (PMID 41362935, 2025). "The correlation between biomarker expression and cancer stage, particularly the higher expression levels in advanced‐stage tumors, suggests that RhoA and Rac1 could serve as reliable indicators of tumor progression." (PMID 39887960, 2025). "Thus, the polycystin‐1/RhoA/YAP pathway not only mediates tumor cell mechanotransduction but also facilitates EMT by coupling mechanical cues to transcriptional programs that drive invasiveness." (PMID 40789101, 2025). "In conclusion, hybridization offered advantages by promoting cytoskeletal rearrangement through “inside” autophagy/RhoA signaling, facilitating the “outside” intra- and intercellular delivery processes, and ultimately increasing lipid nanoparticle accumulation at tumor sites." (PMID 39747218, 2025). "In summary, RHOA-mediated mitochondrial reshaping might serve as a key regulator in tumor cell adaptation and migration in low-oxygen environments." (PMID 40600795, 2025). "Furthermore, concomitant treatment with FDA-approved dacarbazine and simvastatin or fluvastatin suppressed both tumor growth and metastasis in murine models by attenuating the RhoA/RhoC pathway." (PMID 38540310, 2024). "Collectively, the presented data suggest that the levels of Mdmx in tumours may be a critical determinant for the efficacy of NEDD8 inhibitors in the clinic through control of RhoA stability/activity." (PMID 39404389, 2024).
tumor (continued). "Furthermore, the western blot analyses showed that the RhoA signaling was also upregulated in AGS‐DDR1 tumor xenografts, and DDR1 overexpression promoted EMT process in tumor xenografts." (PMID 39024501, 2024). "Consequently, inhibiting the expression of plexinB1 through RNAi-expressing vectors or blocking the RhoA/ROCK signaling pathway proved effective in reducing VM formation by NSCLC tumor cells." (PMID 38375479, 2024). "Indeed, RhoA knockdown reduces tumor cell invadopodium formation, matrix degradation, and intravasation." (PMID 39555068, 2024). "ROCK signaling has been shown to be upregulated in KRAS mutant NSCLC cell lines, animal models, and tumor tissues derived from patients, and it is thought that the increased stiffness of the extracellular matrix of the tumor, combined with hypoxia, activates the RhoA/ROCK pathway." (PMID 38921484, 2024). "Altered RHOA signaling could potentially impact T cell function and infiltration into the tumor microenvironment, influencing immunotherapy response." (PMID 39050251, 2024). "For instance, collagen regulates the extension of invadopodia through the integrin αvβ3/Dishevelled-associated activator of morphogenesis 1 (DAAM1)/Ras Homolog family member A (RHOA)-dependent cascade, which are small actin-rich protrusions that mediate the invasion of tumor cells." (PMID 39769286, 2024). "In our study, scRNA‐seq data showed that the RhoA/ROCK1 pathway was obviously enriched in OXA‐resistant GC samples, suggesting that RhoA/ROCK1 may play a key role in tumor matrix stiffness." (PMID 39392399, 2024). "In SCaBER, loss of ras homolog family member A (RHOA) GTPase activity was demonstrated to be associated with co‐regulation of eukaryotic translation initiation factor 4E family member 3 (EIF4E3), a potential tumor suppressor gene." (PMID 38429970, 2024). "We then sought to determine the direct effect on tumour cells of the combined opposite targeting of p110δ PI3K and RhoA by investigating first whether this treatment affects the proliferation rate and apoptosis of tumour cells." (PMID 38182748, 2024). "Functionally, extracellular H2O2 gradient could induce chemotaxis in tumor cells by activating Src and subsequently inhibiting RhoA, which contributed to ROS gradient-induced spheroid invasion." (PMID 38279020, 2024). "RhoA activation in tumor cells leads to osteosarcoma metastasis to the lung." (PMID 37197432, 2023). "In addition, it has been reported that overexpression of CCR7 in HNSCC tissues facilitated the RhoA/ROCK pathway-mediated migration of tumor cells in HNSCC." (PMID 37600570, 2023). "The RhoA/ROCK signaling pathway is involved in TGF-β1-mediated tumor cell metastasis." (PMID 37175948, 2023). "Moreover, the mechanism responsible for metastasis inhibition by MME seems to be associated with decreased activation of FAK, RhoA, and downstream MEK/ERK, which are involved in tumor migration and metastasis." (PMID 37585411, 2023). "RHOA expression in tumor samples is higher than in normal tissues." (PMID 36982429, 2023). "Thus, it became clear that administration of 17-DMAG also reduced RhoA and Src signaling, indicating that both the proliferation and motility of tumor cells were significantly reduced." (PMID 37547755, 2023). "Seemingly restricted to tumor cells, RHOA mutations are present in approximately 50-70% of AITL cases, with the G17V missense mutation (valine substitution for the 17th residue (glycine)), accounting for 91% of RHOA mutations." (PMID 37188182, 2023). "Expression of RhoA in NFs exerts tumor-suppressive effects by inhibiting tumor motility and growth in vitro and in vivo, maintains tumor epithelial features, and low stiffness, and suppresses inflammation and cancer cell stemness, while, in contrast, its suppression in CAFs drives tumors." (PMID 37046676, 2023).
tumor (continued). "Primary AITL cases showed a correlation between RHOA-G17V mutation allele frequency and collagen fibrosis of the tissue, suggesting that mechanisms leading to extracellular matrix degradation contribute to the early spread of AITL tumor cells." (PMID 37370838, 2023). "Indeed, RHOA knockdown decreased tumor growth and angiogenesis in a breast cancer MDA-MB-231-xenograft mice model." (PMID 36766776, 2023). "Additionally, RhoA was reported to be crucial for cell motility, suggesting an important role for this small GTPase in the invasive phenotype of the tumor cells." (PMID 36766776, 2023). "Of special interest, RhoA and RhoC deletion significantly impaired tumor formation, suggesting that the ablation of the GTPase might lead to a pro-tumoral compensatory mechanism." (PMID 36766776, 2023). "The RHOA/YAP pathway plays a role in tumor-stromal interactions." (PMID 37895915, 2023). "In contrast to other mutations such as TET2 and DNMT3A, which can occur in both tumor and nontumor cells of AITL patients, RHOA mutations appear to be limited to tumor cells, indicating that they play an important role in AITL pathogenesis." (PMID 38023160, 2023). "C-Met-mediated ras homolog family member A (RhoA)/Rho-associated protein kinase (ROCK) signaling and epithelial-to-mesenchymal transition (EMT), characterized by loss of cell polarity, play important roles in tumor invasion and metastasis." (PMID 36046834, 2022). "The process by which tumor cells generate highly patterned vascular channels by relocating the F-actin cytoskeleton is characterized as VM, suggesting that RhoA might play a role in progression." (PMID 36207695, 2022). "In addition, RhoA and RhoC are carcinogenic and related to cell proliferation, migration, and invasion, whereas RhoB is a tumor suppressor and promotes cell apoptosis." (PMID 36320006, 2022). "Then, it was confirmed that miR-210 could regulate EFNA3 expression; further mechanistic analysis revealed that miR-210 could promote tumor progression via the PI3K/AKT/VEGFA or Wnt/Β-catenin/RHOA pathways." (PMID 36466111, 2022). "Furthermore, integrins are involved in the regulation of tumor cell motility through the transforming protein RhoA (RHOA) signaling pathway." (PMID 35409206, 2022). "Its family members, including ras-related C3 botulinum toxin substrate 1 (Rac1), ras homolog family member A (RhoA), and cell division cycle 42 (Cdc42), are engaged in the regulation of the morphology, cell-matrix adhesion, and cytoskeletal reorganization of tumor cells." (PMID 36230880, 2022). "Furthermore, it has been confirmed that circ-IARS is enriched in signaling exosomes secreted by tumor cells and can be transferred to endothelial cells to act as a sponge to adsorb miR-122 and weaken its inhibition of ras homolog family member A (RhoA)." (PMID 35729650, 2022). "Additionally, RHOA and IDH2 mutations are restricted to tumor cells, indicating that they are likely the second hit in a multistep oncogenic process." (PMID 35625998, 2022). "Nuclear accumulation of RAC1 promotes nuclear plasticity, causing a loss of cytoplasmic active RAC1 with a concomitant increase in RhoA that drives actomyosin-mediated changes in cell morphology, the two attributes contribute to intensifying the aggressiveness of tumor cells." (PMID 35013128, 2022). "RHOA/ROCK can also remodel the ECM in the tumor microenvironment to facilitate HCC cell invasion." (PMID 36348464, 2022). "Moreover, molecular analysis of HDI effects disclosed their ability to counteract tumor cell motility by affecting the RhoA-GTPase and the interferon pathways, supporting their further characterization as potential anti-GBM agents." (PMID 35454804, 2022). "The degree of RhoA expression was linked to tumor TNM stage (P = 0.002) and LNM (P = 0.001), but not to other clinicopathological factors (P > 0.05)." (PMID 36207695, 2022).